PDZK1IP1 (PDZK1 interacting protein 1)
Description:
Auxiliary protein of electrogenic Na(+)-coupled sugar symporter SLC5A2/SGLT2 and SLC5A1/SGLT1. Essential for the transporter activity of SLC5A2/SGLT2 but not SLC5A1/SGLT1.
Synonyms: MAP17; DD96; SPAP
Tractability: Small molecule: a structure with a bound ligand is known. Antibody: UniProt places it where antibodies can reach, with high confidence; UniProt predicts a signal peptide or a membrane-spanning region; its Gene Ontology location is reachable by antibodies, with medium confidence.
Gene: Protein-coding gene on chromosome 1 (47,183,582 to 47,191,398, reverse strand). Ensembl gene ENSG00000162366.
Subcellular location: Apical cell membrane
Subcellular location (Human Protein Atlas): Cytosol; Nuclear speckles
Gene Ontology:
Molecular function: protein binding
Biological process: D-glucose import across plasma membrane
Cellular component: extracellular exosome; transmembrane transporter complex; apical plasma membrane
Genetic constraint (gnomAD): Loss-of-function variants: 9 observed, 13.76 expected, observed/expected ratio (o/e) 0.65, 90% interval 0.39 to 1.14. The upper end of that interval is the gene's LOEUF score, 1.14, which puts it in group 5 of 6, group 1 being the genes least tolerant of losing a copy. Missense variants: 152 observed, 139.73 expected, observed/expected ratio (o/e) 1.09, 90% interval 0.95 to 1.25. Synonymous variants: 70 observed, 57.04 expected, observed/expected ratio (o/e) 1.23, 90% interval 1.01 to 1.5.
Homologues: Orthologues: chimpanzee PDZK1IP1 (98% identical), dog PDZK1IP1 (86% identical), guinea pig PDZK1IP1 (82% identical), mouse Pdzk1ip1 (82% identical), rat Pdzk1ip1 (82% identical), tropical clawed frog PDZK1IP1 (30% identical), zebrafish pdzk1ip1 (29% identical). Paralogues in human: SMIM24 (25% identical).
Diseases named in the same sentence as PDZK1IP1 in open-access papers:
PDZK1IP1 is named in the same sentence as 101 diseases in open-access papers, as found by Europe PMC text mining. Sharing a sentence is not in itself a finding about the gene and the disease. The quoted sentences say what the papers report.
breast carcinoma (12 papers, 2012 to 2025). "One study showed that the overexpression of PDZK1IP1 inhibited bortezomib-induced autophagy of breast cancer." (PMID 36978587, 2023). "Studies have shown that the overexpression of PDZK1IP1 inhibits bortezomib-induced autophagy in breast cancer, while the effect of PDZK1IP1 on autophagy regulation in goat subcutaneous preadipocytes has not been reported before." (PMID 36978587, 2023). "In addition, it is worth noting that bortezomib can induce autophagy in breast cancer cells, while overexpressed PDZK1IP1 can inhibit autophagy in these cells." (PMID 36978587, 2023).
cervical carcinoma (8 papers, 2013 to 2023). A carcinoma arising from either the exocervical squamous epithelium or the endocervical glandular epithelium. "The high levels of PDZK1IP1 predict an appropriate response and survival among patients with cervical carcinoma treated with cisplatin and radiotherapy." (PMID 37535601, 2023). "One study revealed that PDZK1IP1 and SGLT1 expression are key prognostic biomarkers for patients with cervical cancer receiving cisplatin plus radiotherapy." (PMID 36737832, 2023).
laryngeal carcinoma (7 papers, 2015 to 2025). Carcinoma that arises from the laryngeal epithelium. "In patients with laryngeal cancer, PDZK1IP1 expression is correlated with higher rates of laryngoesophageal dysfunction–free and overall survival." (PMID 36737832, 2023).
colorectal cancer (5 papers, 2018 to 2025). A primary or metastatic malignant neoplasm that affects the colon or rectum. "For example, SE-driven PDZK1 interacting protein 1 (PDZK1IP1) enhances the reductive capacity of colorectal cancer cells through the pentose phosphate pathway." (PMID 40032852, 2025). "Here, the authors perform epigenomic profiling on primary colorectal cancers (CRCs) and their matched normal tissues and show that local tumour microenvironment induces a SE activation and that its target, PDZK1IP1 promotes CRC growth." (PMID 36253360, 2022). "Targeted therapy that reduces inflammation to lower the level of expression of PDZK1IP1 could be of benefit for patients with colorectal cancer." (PMID 36253360, 2022).
lung carcinoma (5 papers, 2014 to 2025). "The present study also indicated that the relative mechanisms of SLC34A2 in A549 lung cancer may be associated with the activation of the complement alternative pathway (C3 and C4b) and upregulation of the expression of SELENBP1, TXNIP, PDZK1IP1 and DUSP6." (PMID 25017204, 2014). "In patients with lung adenocarcinoma, PDZK1IP1 expression may be used to predict a patient’s response to cisplatin, carboplatin, EGFR inhibitors, or bortezomib, which is clinically beneficial for patients with lung cancer." (PMID 36737832, 2023).
larynx cancer (4 papers, 2015 to 2018). A primary or metastatic malignant neoplasm involving the larynx. "In this study, we evaluated retrospectively 53 patients with larynx cancer to determine whether gH2AX phosphorylation (pH2AX) alone or in combination with the membrane protein MAP17 (PDZK1IP1) could be used as prognostic biomarkers." (PMID 27166270, 2016).
Stroke (4 papers, 2019 to 2023). Sudden impairment of blood flow to a part of the brain due to occlusion or rupture of an artery to the brain. "A single-nucleotide polymorphism in the PITX2 and ZFHX3 genes and two other significantly associated genes, ZNF566 and PDZK1IP1, increase the risk of stroke." (PMID 35741740, 2022). "AF and stroke are related and ZNF566, PDZK1IP1, ZFHX3, and PITX2 genes are significantly associated with novel biomarkers involved in AF-related stroke." (PMID 30760287, 2019). "Thus, there is an association between AF and stroke, and expression of ZNF566, PDZK1IP1, ZFHX3, and PITX2 genes favor AF-related stroke." (PMID 30760287, 2019). "Finally, co-expressed DEGs of ZNF566, PDZK1IP1, ZFHX3, and PITX2 coupled with corresponding predicted miRNAs, especially miR-27a-3p, miR-27b-3p, and miR-494-3p may be significantly associated with AF-related stroke." (PMID 30760287, 2019). "Additionally, co-DEGs of ZNF566, PDZK1IP1, ZFHX3, and PITX2 link AF and stroke." (PMID 30760287, 2019).
thyroid cancer (4 papers, 2018 to 2026). "This study systematically investigated the oncogenic and immunological functions of PDZK1IP1 via a pan-cancer analysis, with experimental validation in thyroid carcinoma (THCA)." (PMID 41761346, 2026).
familial renal glucosuria (2 papers, 2020 to 2025). Familial Renal Glucosuria (FRG) is characterized by the presence of persistent isolated glucosuria in the absence of both generalized proximal tubular dysfunction and hyperglycemia. "Further studies in a cohort of patients with familial renal glucosuria, a condition where glucose is excreted in the urine, revealed that one patient had a splicing mutation in the MAP17 gene (PDZK1IP1) rather than a mutation in the SGLT2 gene itself." (PMID 41322097, 2025).
pancreatic adenocarcinoma (2 papers, 2022 to 2025). "High mRNA expression of PDZK1IP1 negatively prognosticates patient survival in multiple cancers including low-grade gliomas, glioblastomas, pancreatic adenocarcinoma, but not CRC using data from TCGA." (PMID 36253360, 2022).
prostate carcinoma (2 papers, 2014 to 2021). A carcinoma that arises from epithelial cells of the prostate gland. "While the function of PDZK1IP1 has not been evaluated in mast cells, overexpression of PDZK1IP1 has been documented in human ovarian, breast, and prostate carcinomas and this strongly correlates with tumor progression." (PMID 24517413, 2014).
Arthritis (1 paper, 2020). Inflammation of a joint. "Finally, we identify ST6GALNAC1 as a marker of undifferentiated arthritis and MSA4A, PDZK1IP1 and EPHB2 whose expression profiles may potentially discriminate untreated early RA from UA and SLA." (PMID 32483203, 2020).
colon cancer (1 paper, 2014). "PDZK1IP1 exhibited a tumor-suppressor phenotype in cultured colon cancer cells by negatively affecting proliferation and tumor growth." (PMID 25017204, 2014).
inflammatory bowel disease (1 paper, 2022). A spectrum of small and large bowel inflammatory diseases of unknown etiology. "Lastly, examination of previously published single-cell RNA-seq dataset from non-malignant inflamed colon from patients with inflammatory bowel disease show increased expression of PDZK1IP1 (see Methods section for accessions)." (PMID 36253360, 2022).
Insulin resistance (1 paper, 2011). Increased resistance towards insulin, that is, diminished effectiveness of insulin in reducing blood glucose levels. "In future it has to be validated if the other most differentially regulated genes between both tissues such as: SGCD, LCE3D, EREG, NDP and CXCL9, FSTL3, PDZK1IP1 could be used as biomarkers related to insulin resistance of adipose or liver tissues respectively." (PMID 21978410, 2011).
lymph node metastasis (1 paper, 2023). "In addition, tumors with lymph node metastasis and gross ECE exhibited lower PDZK1IP1 expression than those with micro-ECE and no ECE." (PMID 36737832, 2023).
oral cancer (1 paper, 2023). "Therefore, PDZK1IP1 is a potential target gene of miR-455-5p and affects oral cancer outcomes by regulating EMT." (PMID 36737832, 2023).
renal cell carcinoma (1 paper, 2018). "MAP17, also known as PDZK1IP1, DD96 or SPAP, was identified as an upregulated gene in the malignant epithelial cells of renal cell carcinomas." (PMID 29650022, 2018).
cancer (31 papers, 2012 to 2026). A tumor composed of atypical neoplastic, often pleomorphic cells that invade other tissues. "BACKGROUND: PDZK1IP1 is a membrane protein linked to inflammation and cancer, but its role in the tumor immune microenvironment is poorly understood." (PMID 41761346, 2026). "The cargo protein MAP17 (PDZK1IP1) regulates the immune microenvironment and is linked to chronic inflammation, a key factor in cancer development." (PMID 40892863, 2025). "While all studies over-expressed PDZK1IP1, they used different cancer cell lines with different lineage and mutation backgrounds to measure its effect." (PMID 36253360, 2022). "This shows that PDZK1IP1 is highly associated with cancer progression." (PMID 36978587, 2023). "Previous reports had unveiled that PDZK1IP1 is overexpressed in multiple of cancers and involved with tumor stemness." (PMID 37403034, 2023). "PDZK1IP1 or MAP17 which is regarded as a small membrane protein is overexpressed in various carcinoma." (PMID 37535601, 2023). "We demonstrate mechanistically that PDZK1IP1 enhances the reductive capacity CRC cancer cells via the pentose phosphate pathway." (PMID 36253360, 2022). "MAP17 (PDZK1IP1) is a small protein regulating inflammation and tumor progression, upregulated in a broad range of carcinomas." (PMID 33106480, 2020). "Given that interactions between nervous system and cancer cells can promote cancer progression, we hypothesized that patients with co-high expression of notable interactions (APOD_VDAC1, APOD_PDZK1IP1, and CLDN4_APOD) would have poor prognosis." (PMID 40052442, 2025). "Previously, it was shown that PDZK1IP1 was rarely expressed in normal tissue but highly expressed in tumor tissue, and PDZK1IP1 may be an oncogene that is correlated with cancer development." (PMID 36978587, 2023). "LINC00853 exerted a cancer-promoting role in GC through FOXP3-mediated transcription of PDZK1IP1." (PMID 37403034, 2023). "In cancer cells, we find PDZK1IP1 facilitates surplus glucose uptake via SGLT glucose transporters." (PMID 36253360, 2022). "Among the proliferation‐associated genes analyzed—including MKI67, PCNA, MCM2–7, MAP17 (PDZK1IP1), and PLK1—many demonstrated strong positive correlations with C1GALT1 expression in cancers such as pancreas, bladder, breast, stomach, prostate, and liver." (PMID 40548474, 2025). "According to data from the Cancer Genome Atlas database and the NCKU-OrCA-40TN data set, miR-455-5p and PDZK1IP1 are positively and negatively correlated, respectively, with partial EMT score." (PMID 36737832, 2023). "Similarly, a 4-gene (TOP2A, SLC22A1, PDZK1IP1, RDH16) combination for predicting cancer recurrence was selected." (PMID 35422802, 2022). "MAP17 (PDZK1IP1) is a small, 17 kDa non-glycosylated membrane protein located in the plasma membrane and Golgi apparatus and is overexpressed in a wide variety of human carcinomas." (PMID 30250642, 2018).
tumor (27 papers, 2012 to 2026). "One normal colon epithelium case in our cohort met ROSE criteria for PDZK1IP1 SE calling, further suggesting tumor initiating mutations may be dispensable for induction." (PMID 36253360, 2022). "CONCLUSIONS: Our study identified PDZK1IP1 with dual functions, acting as both an oncogene and a modulator of the tumor immune microenvironment." (PMID 41761346, 2026). "This study identifies potential treatment vulnerabilities by focusing on MAP17 (PDZK1IP1), whose high mRNA expression correlates with poor prognosis and is found exclusively in tumor cells." (PMID 40805270, 2025). "Although some studies have reported that PDZK1IP1 has tumorigenic functions, others have reported that it has tumor-suppressive abilities." (PMID 36737832, 2023). "We show this activation enables efficient growth under oxidative conditions, challenging the previous notion that PDZK1IP1 acts as a tumor suppressor in CRC." (PMID 36253360, 2022). "Taken together, our data demonstrate PDZK1IP1 is more important for tumor cell growth in mice, where it can be induced, than in tissue culture where expression is low." (PMID 36253360, 2022). "Our data show this function of PDZK1IP1 endows tumor cells with a growth advantage in the tumor microenvironment but not in tissue culture." (PMID 36253360, 2022). "Here, we identify that one of the most highly recurrent SEs in CRC upregulates the expression of PDZK1IP1 and that this is activated by inflammatory cytokines and the tumor microenvironment." (PMID 36253360, 2022). "Taken together, these mechanistic experiments demonstrate RELA and STAT3 as required for cytokine and tumor microenvironment signaling to PDZK1IP1 induction." (PMID 36253360, 2022). "Our findings argue that the tumor microenvironment activates PDZK1IP1 in colorectal epithelial cells where it acts as an oncogenic driver of tumor growth in collaboration with genetic drivers of the disease." (PMID 36253360, 2022). "To better understand PDZK1IP1 epigenetic regulation by the microenvironment, we queried bulk tumor ATAC-seq and RNA-seq datasets from TCGA21." (PMID 36253360, 2022). "MAP17 (PDZK1IP1) is a small membrane-bound protein whose upregulation is reported as a common feature in tumours from diverse histological origins." (PMID 30119639, 2018). "Moreover, there is evidence that PDZK1IP1 has a widespread impact on tumor cell biological functions, including proliferation, apoptosis, migration, invasion and so on." (PMID 36978587, 2023). "Here we hypothesized that LINC00853 modulated tumor progression and stemness through regulation of PDZK1IP1." (PMID 37403034, 2023). "Interestingly, inflammation in the tumor microenvironment results in the formation of super-enhancers at the PDZK1IP1 gene locus, resulting in colon cancer cell proliferation in vitro and tumor progression in a mouse model." (PMID 38135679, 2023). "PDZK1IP1 is highly expressed in tumor tissue and has been identified as a tumor biomarker." (PMID 36978587, 2023). "Taken together, our data suggest the role of PDZK1IP1 in regulating reductive capacity may be functionally relevant to facilitating CRC tumor growth." (PMID 36253360, 2022). "The mechanism by which PDZK1IP1 regulates tumor growth remains incompletely understood." (PMID 36253360, 2022). "We next assessed the effects of SE induction on PDZK1IP1 expression, using antibodies and quantitative real-time PCR (qRT-PCR) primers specific to human PDZK1IP1 to exclude any signal contribution from mouse cell xenograft tumor infiltrates." (PMID 36253360, 2022). "NAC did not increase tumor growth of sgNeg cells, indicating the growth advantage is not general, but rather specific to the setting of PDZK1IP1 loss." (PMID 36253360, 2022). "Indeed, the tumor-microenvironment and inflammation mediated SE at PDZK1IP1 may fall into this latter category—ubiquitous in primary CRC, yet rare in CRC cell lines (purely cell-intrinsic) as well as inflamed non-dysplastic colon (purely cell-extrinsic)." (PMID 37415185, 2023).
tumor (continued). "Mechanistically, LINC00853 promoted PDZK1IP1 expression through binding to FOXP3, thus maintaining tumor stemness and accelerating tumor progression." (PMID 37403034, 2023). "According to the information of Ensembl database, LINC00853 is located upstream of gene PDZK1IP1 (MAP17), and PDZK1IP1 is also found to be highly expressed in tumors and related to tumor cell stemness." (PMID 37403034, 2023). "To verify the effect of PDZK1IP1 on OSCC migration in vivo, we cultivated PDZK1IP1-knockdown OEC-M1 cells with luciferase-labeling genes and performed intravenous tumor cell injection to observe potential lung metastasis." (PMID 36737832, 2023). "As a proof-of-principle that the PDZK1IP1 SE is under cell-extrinsic control by the tumor environment, we grew the CRC cell line HT29, which expresses low levels of PDZK1IP1, in culture or as subcutaneous xenografts in nude mice." (PMID 36253360, 2022). "Remarkably, PDZK1IP1 was critical for CRC tumor growth in vivo but not in vitro." (PMID 36253360, 2022). "Moreover, PDZK1IP1 SE status failed to correlate with individual somatic protein-coding mutations at other loci, microsatellite instability (MSI), or tumor stage." (PMID 36253360, 2022).
cardiovascular diseases (1 paper, 2021). "Few studies have revealed the role of PDZK1 interacting protein 1 (PDZK1IP1) in cardiovascular diseases; however, PDZK1IP1 acts as a potential biomarker and is abnormally expressed in tumors." (PMID 34753383, 2021).
PDZK1IP1 also shares sentences with these, for which no sentence is quoted: pulmonary hypertension (10 papers); cervical tumors (6); sarcoma (6); breast tumor (5); adenocarcinoma (3); atrial fibrillation (3); gastric cancer (3); heart failure (3); hepatocellular carcinoma (3); metastatic tumors (3); multiple myeloma (3); pancreatic cancer (3); adenoma (2); benign tumors (2); chronic renal failure (2); Crohn disease (2); dental caries (2); heart disease (2); hematological diseases (2); infection (2); lung adenocarcinoma (2); lung fibrosis (2); lupus (2); mantle cell lymphoma (2); non-small cell lung carcinoma (2); pericardial effusion (2); psoriasis (2); rectal cancer (2); AIDS (1); amyloid cardiomyopathy (1).
A further 50 diseases each share a sentence with PDZK1IP1 in 1 paper.